MAD1L1 (mitotic arrest deficient 1 like 1)
Description:
Component of the spindle-assembly checkpoint that prevents the onset of anaphase until all chromosomes are properly aligned at the metaphase plate. Forms a heterotetrameric complex with the closed conformation form of MAD2L1 (C-MAD2) at unattached kinetochores during prometaphase, recruits an open conformation of MAD2L1 (O-MAD2) and promotes the conversion of O-MAD2 to C-MAD2, which ensures mitotic checkpoint signaling. [Isoform 3]: Sequesters MAD2L1 in the cytoplasm preventing its function as an activator of the mitotic spindle assembly checkpoint (SAC) resulting in SAC impairment and chromosomal instability in hepatocellular carcinomas.
Synonyms: HsMAD1; MAD1; TXBP181; PIG9; TP53I9; MVA7
Tractability: PROTAC: UniProt records ubiquitination sites on it; ubiquitination databases record sites on it; its protein half-life has been measured.
Gene: Protein-coding gene on chromosome 7 (1,815,787 to 2,233,243, reverse strand). Ensembl gene ENSG00000002822.
Subcellular location: Nucleus; Chromosome, centromere, kinetochore; Nucleus envelope; Cytoplasm, cytoskeleton, microtubule organizing center, centrosome; Cytoplasm, cytoskeleton, spindle; Cytoplasm, cytoskeleton, spindle pole; Cytoplasm (Isoform 3)
Subcellular location (Human Protein Atlas): Nuclear membrane; Nucleoplasm
Pathways (Reactome):
Cell Cycle: Amplification of signal from unattached kinetochores via a MAD2 inhibitory signal; EML4 and NUDC in mitotic spindle formation; Mitotic Prometaphase; Resolution of Sister Chromatid Cohesion; Separation of Sister Chromatids
Signal Transduction: RHO GTPases Activate Formins
Gene Ontology:
Molecular function: identical protein binding; kinetochore binding; protein binding
Biological process: mitotic spindle assembly checkpoint signaling; positive regulation of mitotic cell cycle spindle assembly checkpoint; regulation of metaphase plate congression; attachment of mitotic spindle microtubules to kinetochore; regulation of mitotic cell cycle phase transition
Cellular component: cytoplasm; kinetochore; MAD1 complex; mitotic spindle; mitotic spindle assembly checkpoint MAD1-MAD2 complex; mitotic spindle pole; nuclear envelope; nuclear membrane; nuclear pore nuclear basket; nucleoplasm; nucleus; centrosome; cytosol; spindle; spindle pole
Genetic constraint (gnomAD): Loss-of-function variants: 93 observed, 89.95 expected, observed/expected ratio (o/e) 1.03, 90% interval 0.87 to 1.23. The synonymous counts are far from expectation, so gnomAD's model fits this gene poorly and the ratio says little. Missense variants: 1,000 observed, 947.96 expected, observed/expected ratio (o/e) 1.05, 90% interval 1 to 1.11. Synonymous variants: 473 observed, 390.12 expected, observed/expected ratio (o/e) 1.21, 90% interval 1.12 to 1.31.
Homologues: Orthologues: chimpanzee MAD1L1 (99% identical), macaque MAD1L1 (98% identical), guinea pig MAD1L1 (85% identical), dog MAD1L1 (84% identical), rat Mad1l1 (83% identical), mouse Mad1l1 (81% identical), pig MAD1L1 (81% identical), tropical clawed frog mad1l1 (63% identical), zebrafish mad1l1 (53% identical), Caenorhabditis elegans mdf-1 (20% identical).
Diseases named in the same sentence as MAD1L1 in open-access papers:
MAD1L1 is named in the same sentence as 57 diseases in open-access papers, as found by Europe PMC text mining. Sharing a sentence is not in itself a finding about the gene and the disease. The quoted sentences say what the papers report.
schizophrenia (26 papers, 2013 to 2025). A major psychotic disorder characterized by abnormalities in the perception or expression of reality. "A novel GWAS in patients with schizophrenia identified schizophrenia-associated differential 5mC at 242 sites, of which mitotic arrest deficient 1-like 1 (MAD1L1) was robustly differentially methylated." (PMID 38203806, 2024). "Genome-wide association studies (GWASs) indicate that MAD1L1 is related to multiple traits, including self-reported educational attainment, bipolar disorder, and schizophrenia." (PMID 37789379, 2023). "MAD1L1 is involved in mitotic spindle-assembly and genetic variation of MAD1L1 has been associated with schizophrenia and anxiety disorders." (PMID 34798907, 2021). "The MAD1L1 gene has previously been reported as containing risk variants associated with both bipolar disorder and schizophrenia, in multiple studies, and more recently, with ADHD and anxiety." (PMID 32799817, 2020). "Another DMR of interest falls within an intronic region of the mitotic spindle-assembly checkpoint gene MAD1L1, adjacent to a region previously associated with risk for schizophrenia and BD." (PMID 26798408, 2016). "It is also noteworthy that SNPs located close to MAD1L1 were significantly associated with both schizophrenia and bipolar disorder." (PMID 23637625, 2013). "Although large-scale genome-wide association studies (GWAS) have identified an association between MAD1L1 (Mitotic Arrest Deficient-1 Like 1) and the pathology of schizophrenia, the molecular mechanisms underlying this association remain unclear." (PMID 36357673, 2023). "ENSMUST00000199237 was the lncRNA with the highest FoldChange value and is one of the transcripts of Mitotic arrest deficient 1 like 1 (Mad1l1), a susceptibility gene for bipolar disorder and schizophrenia, suggesting a possible role of ENSMUST00000199237 in other neuropsychiatric disorders." (PMID 35955632, 2022). "The locus is novel with respect to ADHD and DBDs, but was found genome-wide significant in the recent large cross-disorder GWAS48 and has previously been associated with schizophrenia and bipolar disorder, suggesting that MAD1L1 is a risk gene for several psychiatric disorders." (PMID 33495439, 2021). "MAD1L1 has been shown to be a target of another schizophrenia-susceptibility gene, miR-137." (PMID 26798408, 2016). "For instance, MAD1L1 (rs1107592) and TSNARE (rs4976976) heterozygotes showed a decreased risk of schizophrenia." (PMID 37124257, 2023). "The locus identified on chromosome 7 (rs56226325, MAF = 0.17) near MAD1L1 was previously identified as PTSD-risk locus in GWASs in Million Veteran Program, and also found in bipolar disorder and schizophrenia [24,25,]." (PMID 34282125, 2021). "Of note, MAD1L1 has strong previous genetic and gene expression data for involvement in autism, as well as in bipolar disorder and schizophrenia." (PMID 30862937, 2020). "Two separate cQTLs in MAD1L1 (PP(H4) > 0.98), one cQTL in AS3MT (PP(H4) = 0.98), one cQTL in TSNARE1 (PP(H4) = 0.94), and one cQTL in RERE (PP(H4) = 0.92) were found to colocalize with schizophrenia-associated variants." (PMID 30087329, 2018). "As expected, there was also limited concordance between schizophrenia and ADHD (r = 0.0705), particularly for downregulated genes, and six (MAD1L1, KDM4A, IPO13, ATP6V0B, DPH2, PTPRF) of the nine placental genes associated with ADHD were also significantly associated with schizophrenia." (PMID 37188697, 2023).
bipolar disorder (12 papers, 2013 to 2025). A disorder of the brain that causes unusual shifts in mood, energy, activity levels and the ability to carry out day-to-day tasks. "The intronic SNP rs11764590 of MAD1L1 is associated with bipolar disorder via functional alterations in the reward system, an intermediate phenotype for bipolar disorder." (PMID 37789379, 2023). "rs4236274 and rs4332037 in the intron regions of MAD1L1 have also been reported to be significantly associated with bipolar disorder in GWASs." (PMID 37789379, 2023). "Finally, multiple GWAS revealed genetic associations of MAD1L1 with bipolar disorder and major depressive disorder, which encourage further investigations regarding the role of MAD1 in major psychiatric diseases." (PMID 36357673, 2023). "The result showed that 6 genes (including MAD1L1, JAM3, MYL12B, MYL12A, ITIH1 and RYR2) had been reported to be significant associated with bipolar disorder in at least one genetic study." (PMID 26193471, 2015).
depression (10 papers, 2019 to 2025). "Our results suggest an association between methylation changes in the MAD1L1 gene in relation to suicide severity and depression." (PMID 36600305, 2023). "The epigenome-wide analysis at screening identified 17 unique CpG sites that reached epigenome-wide significance, 10 of which were located within or nearby the MAD1L1 gene and were associated with either of the four depression-related MAD1L1 SNPs." (PMID 36600305, 2023). "Using a longitudinal EWAS approach in an adolescent cohort at two time points (n = 216 and n = 154), we identified differentially methylated sites that were associated with depression-related genetic variants in MAD1L1." (PMID 36600305, 2023). "In the context of this work, we investigated how previously discovered depression-related single nucleotide polymorphisms (SNPs) at MAD1L1 could mediate their effect through local epigenome-wide significant alterations in DNA methylation." (PMID 36600305, 2023). "Among these genes, MAD1L1 was also positively associated with depression." (PMID 37188697, 2023). "The association of MAD1L1 with depression may be reflected in MAD1L1-interacting proteins and their secondary functions; thus, we have conducted an enrichment analysis for MAD1L1 physical interactors based on the data from the STRING database and its provided GO/pathway analysis tools." (PMID 36600305, 2023). "MAD1L1 protein physically interacts with 11 partners associated with its main mitosis checkpoint function, and these proteins could be potentially related to depression as well." (PMID 36600305, 2023). "For example, among the candidate genes were known susceptibility loci for diabetes (PTPN22, CEP68, RREB1, TCF7L2), coronary artery disease (PSRC1, UNC5C, LPLA), depression (MAD1L1, YLPM1) and insomnia (NMT1)." (PMID 38541061, 2024). "Another study identified the cg08985282 site at MAD1L1 as a depression-related locus based on a comparison of depressed individuals with their healthy monozygotic twins (12 pairs)." (PMID 36600305, 2023). "This is the first study showing associations between DNA methylation and previously identified depression-related SNPs at the MAD1L1 gene and depression and suicidal behavior using multiple independent cohorts." (PMID 36600305, 2023). "This CpG was a Top 1 interacting partner for almost all depression-related MAD1L1 SNPs in mQTL analysis with the additive genetic model as well, and its top 10 interacting SNPs were almost always in LD with depression-related MAD1L1 loci." (PMID 36600305, 2023). "The first step was to identify depression-related SNPs at the MAD1L1 gene based on the previous GWAS." (PMID 36600305, 2023). "For example, differential methylation in CpG probes mapping near MAD1L1 were found in affected depression patients compared with their unaffected monozygotic twins." (PMID 35354486, 2022). "MAD1L1 was an even better predictor by gender and diagnosis in male bipolar (OR 2.1, p = 0.0097) and male depression (OR 31.4, p = 0.0055)." (PMID 30862937, 2020). "Other top associated probes were located in gene bodies of MAD1L1 (p-value = 5.16 × 10−6), SLC29A2 (p-value = 6.15 × 10−6) and AKT1 (p-value = 4.47 × 10−6), all genes associated before with development of depression." (PMID 31477683, 2019). "However, for cg19624444, almost all Top 10 partners were in the linkage disequilibrium with depression-related MAD1L1 loci, and some of the Top 10 partners of cg02825527 were in similar LD at screening." (PMID 36600305, 2023). "Other genes that located outside of the MHC region, such as MAD1L1, RERE, SORCS3 and ANKK1, are associated with neuronal development and guidance of neuronal growth, transcriptional processes and other risk factors for depression, for example, obesity, smoking and abnormal physical development." (PMID 35354486, 2022).
depression (continued). "In conclusion, we have performed EWAS of depression symptomatology score in a unique cohort of elderly monozygotic twins and identified blood methylation levels at KLK8, DAZAP2, MAD1L1, SLC29A2, AKT1, and other genes, as well as several DMRs across the genome to be associated with this trait." (PMID 31477683, 2019).
breast carcinoma (6 papers, 2014 to 2023). "MAD1L1, also known as mitotic arrest deficient-like 1, was associated with a poor prognosis and insensitivity to paclitaxel in breast cancer." (PMID 37496025, 2023). "USP15 stabilizes MDM2, a well-known cancer gene, to regulate cancer-cell survival and mediates antitumor T cell responses, while increased expression of MAD1L1 is associated with poor prognosis in breast cancer." (PMID 31024613, 2019). "Breast cancers and breast cancer cell lines overexpress several mitotic regulators, including kinases that regulate the SAC such as Nek2, Mad1L1, Mad2L1, Mad2L2, BubR1, BubR1B, Bub3, Cdc20, and Mps1/TTK." (PMID 29100415, 2017).
Obesity (5 papers, 2022 to 2025). Accumulation of substantial excess body fat. "Notably, abnormal methylation at MAD1L1 (loci cg08972190) has been reported in children surviving ALL, particularly in association with obesity and exposure to cranial radiotherapy." (PMID 41226303, 2025).
colorectal cancer (4 papers, 2015 to 2025). A primary or metastatic malignant neoplasm that affects the colon or rectum. "MAD1L1 was strongly associated with cancer progression and the development of colorectal cancer, and its aberrant expression has been reported in solid tumors." (PMID 41226303, 2025). "In the “Other tumors group” four rearrangements involving BRAF gene were detected (three melanoma: BRAF::CNNM2, BRAF::ERC1, BRAF::MAD1L1 and one pancreatic adenocarcinoma BRAF::SND1), but also one ETV6::NTRK3 (colorectal cancer) and one FGFR3::TACC3 (urothelial cancer)." (PMID 37708140, 2023).
diabetes (3 papers, 2023 to 2025). "Of the top 15 genes presenting differential methylation in both phenotypes, MAD1L1, TUBB, HIST1H2AL and TBCA were significantly associated with diabetes-related phenotypes in the UK Biobank." (PMID 37239390, 2023).
lung carcinoma (3 papers, 2015 to 2023). "This is a low minor allele frequency (MAF) based on the NCBI database [A = 0.000004/1 (GnomA Dexomes)], but some investigators have found a polymorphism of MAD2L1 rs1283639804 in combination with the polymorphism of MAD1L1 rs1801368 conferring colorectal and lung cancers." (PMID 37007941, 2023).
melanoma (3 papers, 2013 to 2023). A malignant, usually aggressive tumor composed of atypical, neoplastic melanocytes. "Expression of FAM174B, MAD1L1, SCARB1, MFSD12, SEMA6A, SLC45A2, and TBC1D16 was found to be upregulated and associated with worse OS in melanoma patients, while only MFSD12 and SLC45A2 were associated with worse DFS for melanoma patients." (PMID 30385854, 2019). "Specifically, FLRT2 was downregulated while MAD1L1, PHLDA2, PLAT, CC2D1B, CDKN2A and RUNX3 were upregulated in both melanoma and in Group 2 and Group 3 SFs." (PMID 23371019, 2013).
coronary artery disease (2 papers, 2023 to 2024). "The Cohorts for Heart and Aging Genetic Epidemiology (CHARGE) Consortium has performed the largest prospective EWAS of coronary heart disease to date and reported associations with DNAm in PTPRN2 and MAD1L1." (PMID 37533055, 2023).
glioma (2 papers, 2011 to 2023). A benign or malignant brain and spinal cord tumor that arises from glial cells (astrocytes, oligodendrocytes, ependymal cells). "In this study, we explored the molecular functions of CHPF and its associations with Mitotic arrest deficient 1-like 1 (MAD1L1) in glioma." (PMID 37851364, 2023). "The results showed that CHPF was directly interacted with MAD1L1 to promote glioma progression by regulating cell cycle." (PMID 37851364, 2023). "In our study, inhibition of glioma by downregulation of CHPF was reversed by overexpression of MAD1L1, which showed that CHPF promoted glioma malignance through regulation of MAD1L1 expression." (PMID 37851364, 2023). "Furthermore, CHPF promoted glioma tumorigenesis through direct interaction with MAD1L1 and regulation of MAD1L1 expression." (PMID 37851364, 2023). "Expression of six SAC genes, BUB1, BUB1B, CDC20, CENPE, MAD1L1 and TTK were found to be significantly positively correlated with WHO grades of glioma patients (p<0.01)." (PMID 22022424, 2011). "RNA levels of eight major mitotic spindle assembly checkpoint (SAC) genes (BUB1, BUB1B, BUB3, CENPE, MAD1L1, MAD2L1, CDC20, TTK) significantly correlated with glioma grade and six also significantly correlated with survival time." (PMID 22022424, 2011).
hepatocellular carcinoma (2 papers, 2021 to 2025). A malignant tumor that arises from hepatocytes. "MAD1L1 (a component of the mitotic spindle‐assembly checkpoint) has a role in cell cycle control and tumor suppression and methylation levels have been strongly correlated with hepatocellular carcinoma." (PMID 33842847, 2021).
Hypertension (2 papers, 2023 to 2024). The presence of chronic increased pressure in the systemic arterial system. "MAD1L1 (mitotic arrest deficient 1 like 1) encodes a component of the mitotic spindle assembly checkpoint and is a shared and consistent signal of association between IPF and hypertension." (PMID 37965228, 2023).
idiopathic pulmonary fibrosis (2 papers, 2021). Idiopathic pulmonary fibrosis (IPF) is a nonneoplastic pulmonary disease that is characterized by the formation of scar tissue within the lungs in the absence of any known cause. "MAD1L1 was identified as a genome-wide significant signals with idiopathic pulmonary fibrosis by GWAS." (PMID 34809630, 2021).
nasopharyngeal carcinoma (2 papers, 2021 to 2022). A carcinoma arising from the nasopharyngeal epithelium. "Yet another effect of RARS on cancers involves gene fusion between RARS and mitotic arrest deficient 1-like protein 1 (MAD1L1), which induces the proliferation of nasopharyngeal cancer cell lines and their chemo- and radio-resistance." (PMID 36017335, 2022). "RARS1 fusion with MAD1L1 has been reported to stimulate the FUBP1/c-Myc signaling pathway, inducing tumorigenesis in nasopharyngeal carcinoma." (PMID 35047511, 2021).
colon cancer (1 paper, 2024). "Reduced expression, mutation and amplification of MAD1L1 are rare (5.7%, 1.2% and 0.3%, respectively) in colon cancer." (PMID 39374311, 2024). "Kaplan-Meier analysis of 1336 colon cancer patients (kmplot.com) demonstrated that high expression of MAD1L1 associates with significantly worse prognosis as measured by relapse free survival." (PMID 39374311, 2024). "Mitotic Arrest Deficient 1 (gene name MAD1L1), an essential component of the mitotic spindle assembly checkpoint, is frequently overexpressed in colon cancer, which correlates with poor disease-free survival." (PMID 39374311, 2024). "Thus, MAD1L1 overexpression commonly occurs in colon cancer and correlates with poor patient outcome." (PMID 39374311, 2024).
cylindroma (1 paper, 2016). "Some genes, such as CD34, that have been described as MYB target genes in ACC 4 were, however, found to be underexpressed in cylindroma (fold change decrease = ×0.47), whilst genes such as MAD1L1 were not differentially expressed between tumours and controls (data not shown)." (PMID 26969893, 2016).
gonococcal infection (1 paper, 2014). "Further, the gonococcal infection upregulated MAD1L1 mitotic arrest deficient-like 1 (encoding the MAD1 protein) by 1.4-fold and downregulated MAD2L1 mitotic arrest deficient-like 1 (encoding the MAD2 protein) by 0.7-fold." (PMID 25460012, 2014).
hair disorders (1 paper, 2023). "These comprise variants within genes associated with various types of human cancer (MAD1L1), Joubert syndrome 23 (KIAA0586), hair disorders (PADI3), mannose-binding lectin deficiency (MBL2), and multiple sclerosis (IL4R)." (PMID 36404349, 2023).